RN7SL530P (RNA, 7SL, cytoplasmic 530, pseudogene)
Gene: Miscellaneous RNA gene on chromosome 14 (74,174,456 to 74,174,753, forward strand). Ensembl gene ENSG00000239910.
Homologues: Orthologues: chimpanzee Metazoa_SRP (99% identical), macaque Metazoa_SRP (92% identical). Paralogues in human: RN7SL2 (83% identical), RN7SL1 (83% identical), RN7SL3 (81% identical), RN7SL709P (81% identical), RN7SL220P (81% identical), Metazoa_SRP (80% identical), RN7SL448P (80% identical), RN7SL627P (80% identical), RN7SL122P (80% identical), RN7SL408P (80% identical), RN7SL88P (80% identical), RN7SL296P (79% identical), and 705 more.